NOD1 (nucleotide binding oligomerization domain containing 1)
Diseases named in the same sentence as NOD1 in open-access papers (continued):
Sharing a sentence is not in itself a finding about the gene and the disease.
colorectal cancer (18 papers, 2009 to 2025). A primary or metastatic malignant neoplasm that affects the colon or rectum. "Moreover, increased NOD1 expression is linked to reduced overall survival in individuals with colorectal cancer." (PMID 39696641, 2024). "Previous studies have confirmed that single nucleotide polymorphism of NOD1 affects the occurring and advancement of various tumors, comprising lung carcinoma, stomach carcinoma, colorectal carcinoma, pancreatic carcinoma, head and neck squamous cellular carcinoma, etc." (PMID 35153782, 2022). "NOD1 was highly expressed in colorectal cancer, and mediated the adhesion, migration and metastasis of colorectal cancer cells through the p38 MAPK pathway." (PMID 36203437, 2022). "By contrast, the expression level of NOD1 is significantly higher than that in adjacent tissues in colorectal cancer." (PMID 36186792, 2022). "Our data demonstrate that NOD1 is highly expressed in human colorectal cancer (CRC) and human and murine CRC cell lines." (PMID 31956962, 2020). "NOD1 is regulated by PSMA7 in a proteasome-dependent manner, and overexpression of PSMA7 inhibits NOD1-mediated colorectal cancer cell apoptosis." (PMID 27966459, 2017). "Nucleotide‐binding oligomerisation domain 1 (NOD1), a cytoplasmic PRR, plays a role in colorectal cancer (CRC) by detecting bacterial products." (PMID 36068649, 2022). "Although no mutations in the NOD1 gene have been so far associated with the incidence of intestinal inflammation or even colorectal cancer (CRC), murine models clearly designate a central anti-tumorigenic function for NOD1 in the pathophysiology of disease." (PMID 25071785, 2014). "As with NLRP6, NOD1 is also a member of the NOD-Like Receptor (NLR), and it could modulate the immunosuppressive activity of myeloid cells in colorectal cancer." (PMID 36823654, 2023). "A recent study demonstrated that activation of NOD1 facilitated oncogenesis by promoting autophagy-dependent macrophage reprogramming and triggering myeloid-derived suppressor cell (MDSC) expansion and immunosuppressive ability through arginase-1 activity in colorectal cancer." (PMID 36920176, 2023). "NOD1 and NOD2 expression were enhanced in colorectal cancer, and NLRC5, NLRP6 and NLRP12 had no significant changes compared to the controls." (PMID 34571825, 2021).
Crohn disease (17 papers, 2009 to 2025). A gastrointestinal disorder characterized by chronic inflammation involving all layers of the intestinal wall, noncaseating granulomas affecting the intestinal wall and regional lymph nodes, and transmural fibrosis. "In this study, we found that LRRK2, encoded by a gene implicated in Crohn’s disease, leprosy and familial Parkinson’s disease, modulates the strength of Nod1/2-Rip2 signaling by enhancing Rip2 phosphorylation." (PMID 27830463, 2017). "Genotypic and allelic distribution of NOD1 rs2075820 polymorphism in Malaysian Crohn’s disease (CD) patients and control individuals." (PMID 27069792, 2016). "Understanding how ATG16L1 properly regulates NOD1/2 activation might pave the way to a better understanding of disease pathogenesis (e.g., for Crohn's disease patients bearing variants in ATG16L1)." (PMID 31803185, 2019). "In human, the deficiency of NOD2 would cause Crohn’s disease and in grass carp, NOD1 and NOD2 could be upregulated by different immunostimulants." (PMID 30119658, 2018). "Thus in addition to providing a genome-wide view of NOD1/2 signalling pathway regulation, our study also provide important leads into the mechanism by which Crohn’s disease susceptibility genes contribute to the disease." (PMID 28656966, 2017). "Accumulating evidence suggests that vitamin D beneficially reduced TLR1 and NOD1 in Crohn’s disease." (PMID 40723565, 2025). "In another study in humans, to understand the pathogenesis of Crohn’s disease, an R protein homolog, the cytosolic NOD1 and NOD2 receptors interacted with ATG16L1 to initiate autophagy of bacteria entering the host cell." (PMID 37936940, 2023). "Genetic variations in NOD1 and NOD2 are associated with increased susceptibility to Crohn's disease." (PMID 29254180, 2017). "The study of NOD2 linkage to Crohn’s disease has been extended to encompass a key role of NOD1 and 2 in the regulation of autophagy." (PMID 24137163, 2013). "The role of NOD1 and 2 in this process was initially proposed following GWAS findings of an association between a key component of the autophagy process, ATG16L1, and susceptibility to Crohn’s disease." (PMID 24137163, 2013). "DNA samples from 388 Crohn's disease (CD), 405 ulcerative colitis (UC), 27 indeterminate colitis patients and 201 randomly selected controls, from Canterbury, New Zealand were screened for 3 common SNPs in NOD1, using the MassARRAY® iPLEX Gold assay." (PMID 19327158, 2009).
gastric cancer (16 papers, 2011 to 2024). A primary or metastatic malignant neoplasm involving the stomach. "NOD1-specific single nucleotide polymorphisms (SNPs) have been associated with H. pylori infection and gastric cancer." (PMID 35463631, 2022). "Nevertheless, after stratification according to histological type, the NOD1 rs2075820 (p.E266K) polymorphism was associated only among cases with intestinal-type gastric cancer in the unadjusted analysis (OR = 2.69, 95% CI 1.41–5.13, P = 2.6 × 10− 3)." (PMID 33879265, 2021). "However, NOD1 rs2075820 (p.E266K) showed association with intestinal-type gastric cancer among H. pylori infected subjects (OR = 2.69, 95% CI 1.41–5.13, p = 0.0026)." (PMID 33879265, 2021). "Little is known about the association of NOD1 rs2075820 with gastric cancer." (PMID 33879265, 2021). "We noticed significant association with NOD1 rs2075820 (OR = 4.90, 95% CI 1.80–13.36, P = 1.9 × 10− 3), in particular in intestinal-type gastric cancer cases (OR = 7.16, 95% CI 2.40–21.33, P = 4.1 × 10− 4) but no among diffuse-type gastric cancer cases (OR = 3.39, 95% CI 1.13–10.10, P = 0.03)." (PMID 33879265, 2021). "H.pylori infection leads to the activation of the NOD1 and NOD2 genes; several variants of which have been observed to be associated with gastric cancer in different populations." (PMID 38867324, 2024). "Evidence shows that NOD1 exerts its restrictive role by altering macrophage polarization in induced gastric cancer, leading to immune evasion and microbial persistence." (PMID 39696641, 2024). "The aim of our study was to assess the association of common polymorphisms in TLR2, TLR4, TLR5, NOD1 and NOD2 with gastric cancer in H. pylori infected subjects." (PMID 33879265, 2021). "The aim of this study was to assess if polymorphisms of TLR2, TLR4, TLR5, NOD1 and NOD2 genes are associated with gastric cancer, in particular in individuals infected with H. pylori." (PMID 33879265, 2021). "Some studies assessing the role of polymorphisms in TLR2, TLR4, TLR5, NOD1 and NOD2 in gastric cancer have been published." (PMID 33879265, 2021). "RIPK2 contributes to both proliferation and invasion in cancers such as ovarian and gastric cancers, mediates NOD1 to regulate the NF-κB pathway, and promotes immunotherapy resistance by triggering cytotoxic T lymphocyte dysfunction, which is highly detrimental to prognosis." (PMID 37031243, 2023). "The Nod1 mRNA expression level was also shown to be upregulated in gastric cancer tissues." (PMID 33194715, 2020). "H. pylori activates NF-κB, inflammation and gastric cancer via Nod1-dependent activation." (PMID 33194715, 2020). "Single nucleotide polymorphisms (SNPs) of NOD1 and NOD2 have been found to be associated with risk of gastric cancers (GC) and precancerous lesions in Caucasian population." (PMID 29254180, 2017). "Previous studies have revealed that NOD1 contributes to tumour development and progression, particularly in CRC and gastric cancer, which originate in sites with high host‐microbiome interactions." (PMID 36068649, 2022). "The aim of our study was to evaluate potential associations between the presence of gastric cancer (GC) and high risk atrophic gastritis (HRAG) and polymorphisms of genes encoding Angiotensin converting enzyme (ACE), Nod-like receptor 1 (NOD1), Toll-like receptor 4 (TLR4) and FAS/FASL." (PMID 21864388, 2011). "In addition, H. pylori can initiate abnormal activation of cellular signaling pathways, such as Nod1-NF-KB/MAPK-ERK/FOXO4 pathway, allowing cells to escape autophagy and leading to the occurrence of gastric cancer." (PMID 35463631, 2022).
atherosclerosis (13 papers, 2014 to 2025). A disease characterized by the build-up of fatty material and calcium deposition in the arterial wall resulting in partial or complete occlusion of the arterial lumen. "We envisage that NOD1 has the potential to contribute to the assessment of the risk of cardiometabolic diseases associated with endothelial damage such as atherosclerosis." (PMID 39906040, 2024). "Since atherosclerosis is the main underlying cause of most of the CVDs and it involves lipid deposition and NOD1 in addition to other important inflammatory and immune components, immunonutrition approaches represent another essential front to fight them." (PMID 34066406, 2021). "Administration of a NOD1 agonist enhanced atherosclerosis in apolipoprotein E (Apoe)-deficient mice, whereas Nod1/Apoe-deficient mice showed reduced atherosclerosis." (PMID 32588196, 2020). "Hence, in the present study we investigated hypercholesterolemic mice deficient for Nod1 as well as for Nod2 in regard to experimental atherosclerosis, lipid metabolism, insulin resistance and gut microbiota composition." (PMID 32588196, 2020). "Advanced plaque analysis in the Apoe−/− atherosclerosis model suggests that NOD1 deficiency may decrease the risk of atherothrombosis by decreasing leukocyte infiltration and reducing macrophage apoptosis." (PMID 32927803, 2020). "There are few studies on the role of the NOD1 signaling pathway in the development of atherosclerosis." (PMID 39640499, 2024). "Knowing that NOD1 is closely related to atherosclerosis and CVDs, a combined immunonutrition–microRNA strategy would be expected to be effective." (PMID 34066406, 2021). "In recent years, scientists have investigated the potential role of NOD1 in atherosclerosis using Nod1 knockout mice." (PMID 30319417, 2018). "Further, in Apoe-/- and Nod1-/- double-knockout mice, atherosclerotic lesion area in aortic root was reduced compared to Apoe-/- knockout mice suggesting a role for Nod1 in atherosclerosis." (PMID 27936005, 2016). "Studies in mice have shown Nod1 to play a role in heart function and atherosclerosis, providing biologic plausibility for a role in bIMT thus making NOD1 an excellent bIMT candidate." (PMID 27936005, 2016). "Studies in mice have revealed Nod1 to have a role in heart function and atherosclerosis, thus providing further biologic plausibility for NOD1’s role in bIMT." (PMID 27936005, 2016). "Our results reinforce the preeminent role for NOD1 in human atherosclerosis." (PMID 32927803, 2020). "In the current study, we detected an effect of Nod1/2-deficiency on experimental atherosclerosis and lipid metabolism, whereas we did not observe effects on insulin resistance." (PMID 32588196, 2020). "The main finding of the present study coincides with our previous observations in human atherosclerosis suggesting a preeminent role for NOD1, a member of the so-called pattern recognition receptors of the innate immunity, not only in endothelial cells, but now also in SMC and macrophages." (PMID 32927803, 2020). "Considering that the mechanism by which NOD1 mediates atherosclerosis is related to its function in promoting the aggregation of leukocyte subpopulations, assessing NOD1 expression on leukocyte subpopulations in the peripheral circulation of subjects may be a feasible approach." (PMID 39906040, 2024).
atherosclerosis (continued). "Thus, the NOD1/Rip2 signaling pathway could contribute to atherosclerosis development by regulating macrophage inflammatory activation." (PMID 39640499, 2024). "Furthermore, the inactivation of Nod1 in the Apoe−/− mouse model of atherosclerosis may contribute to plaque stability by modulating the pathophysiological functions of macrophages and SMCs." (PMID 32927803, 2020). "Peptidoglycan, as the specific ligand of NOD1 and NOD2, has been reported to be involved in atherosclerosis, contributing to the instability of atheromas." (PMID 39640499, 2024). "The analysis of total lipid in the aortic valve of the same mice did not reveal a biological significance for NOD1 in foam-cell formation in advanced atherosclerosis." (PMID 32927803, 2020). "It must be noted however, that the role of NOD1 in atherosclerosis is not yet known." (PMID 24690886, 2014).
viral infection (12 papers, 2010 to 2024). "Induction of ISGs and NOD-like receptor family in our study is consistent with a recent finding that the cross-talk between Nod1/Nod2 receptors and type 1 IFNs induced during a viral infection, promoted lethality in mice superinfected with E. coli." (PMID 23742656, 2013). "Regarding the antiviral capacity of the NOD1 pathway in the context of viral infections, previous results demonstrated that NOD1 agonist DAP inhibits viral replication of HBV in pretreated C57BL/w mice by decreasing HB antigen and DNA levels due to enhanced T cell activation and immune response." (PMID 38791357, 2024). "Moreover, NOD1 can also act as an RNA virus receptor to enhance the immune response during viral infection." (PMID 36825023, 2023). "In addition, NOD1 in fish can also act as the receptor of the RNA virus to enhance the immune response in the virus infection." (PMID 33581111, 2021). "miR-217-5p can reduce the expression of NOD1 and suppress NOD1-mediated innate immune responses, which may be beneficial for bacterial or viral infection." (PMID 33581111, 2021). "In addition, NOD1 can also act as a receptor to enhance the immune response during viral infection." (PMID 36825023, 2023). "In mandarinfish, both the NOD1 and NOD2 gene were found to be activated in viral infection, mimicked by treatment with the viral analogue Poly I:C, revealing that NODs are sensitive to the protective immune response against viral invasion." (PMID 30119658, 2018). "Indeed, authors showed how depletion of NOD1, as well as MDA5 and LGP2, drastically reduced the levels of IFN-β upon SARS-CoV-2 infection, rendering lung Calu-3 permissive to viral infection." (PMID 38791357, 2024). "In addition to differences in the recognition and regulation of bacterial infection, NOD1 and NOD2 also display different functions during viral infections." (PMID 35638852, 2022). "Consistent with the reported requirement for NOD2 but not NOD1 for the IFNβ response following ssRNA virus infection, only a minimal stimulation was observed in 293/hNOD1 cells." (PMID 23936340, 2013). "In addition, we did not observe any cleavage of the upstream receptors NOD1 and NOD2, nor other crucial signaling proteins implicated in innate immune response to virus infection, including MAVS and STING." (PMID 26297639, 2015). "Recent studies have shown that NOD1 activation is mediated in ECs largely, if not entirely, by NOD1 induction of IFN-β and thus a signaling pathway ordinarily activated by viral infection." (PMID 21152124, 2010). "We suggest that as in viral infection, M. ovipneumoniae infection can activate NOD2 but not NOD1." (PMID 32778560, 2020).
diabetes (11 papers, 2018 to 2026). "Hematopoietic NOD1 loss had a protective effect against diabetes, leading to fewer monocyte-derived macrophages residing in the retina of NOD1−/−−-Akita → Akita mice." (PMID 38336763, 2024). "The specific loss of NOD1 in hematopoietic cells mitigated the structural changes in retinal cross-sections caused by diabetes." (PMID 38336763, 2024). "All the data indicate that NOD1 depletion partially resolved the structural alterations caused by diabetes in the cross-section of the retina." (PMID 38336763, 2024). "Although ER stress has been implicated in AS and diabetes, it remains to be elucidated whether the increased inflammatory response after NOD1 and NOD2 stimulation is mediated by UPR activation." (PMID 31109951, 2019). "NOD1 depletion partially restored diabetes-induced structural changes and retinal electrical responses in NOD1−/−-Akita mice." (PMID 38336763, 2024). "NOD1 depletion averted the decline in retinal thickness and the deterioration of retinal electrical responses induced by diabetes." (PMID 38336763, 2024). "We observed that serum extracted from Akita mice 6 months after diabetes onset exhibited greater NOD1-activating potential than did serum extracted from age-matched controls." (PMID 38336763, 2024). "Nucleotide-binding oligomerization domain-containing protein 1 (NOD1) plays a pivotal role in inducing metabolic inflammation in diabetes." (PMID 38336763, 2024). "NOD1 depletion effectively counteracts the diabetes-induced depletion of both LT- and ST-HSCs as well as disruptions in hematopoiesis, redirecting cells toward a more proinflammatory profile." (PMID 38336763, 2024). "Intriguingly, the hematopoietic depletion of NOD1 mitigated the diabetes-induced expression of CXCL1 and CXCL2; TNFα and IL10 remained unaffected." (PMID 38336763, 2024). "In our current investigation, we also established that NOD1 depletion counteracted the diabetes-induced reduction in HSC populations and mitigated the shift toward myelopoiesis." (PMID 38336763, 2024). "A previous study showed that NOD1 is overexpressed in the murine and human myocardium in cases of type 2 diabetes mellitus." (PMID 29760746, 2018). "The high levels of NOD1 in CFs were observed in cardiac human necropsies of type 2 diabetes mellitus patients, supporting the animal model results." (PMID 29760746, 2018). "This suggests that NOD1 depletion improved retinal cell responses to light stimulation in diabetes." (PMID 38336763, 2024). "Elevated circulating NOD1 activators were observed in Akita mice after 6 months of diabetes." (PMID 38336763, 2024). "Notably, the double-mutant mice exhibited a CFU colony-forming capacity akin to that of the WT group, underscoring that NOD1 depletion restored the diabetes-induced hematopoietic imbalance toward myelopoiesis." (PMID 38336763, 2024). "Exendin-4 can ameliorate PA-related pneumonia with diabetes and overexpression of NOD1/NF-κB." (PMID 38748233, 2024). "Moreover, the quantification of acellular capillaries, a hallmark of vascular degeneration in DR, revealed that hematopoietic NOD1 ablation alleviated the diabetes-induced increase in this pathological feature." (PMID 38336763, 2024). "Consistent with our previous RNA sequencing data, our current study showed that a specific NOD1 inhibitor prevented PGN-induced bone marrow neuropathy and HSPC deprivation, further confirming the critical role of NOD1 in PGN-mediated bone marrow defects in subjects with diabetes." (PMID 35966130, 2022). "In this sense, the nucleotide-binding oligomerization domain-1 (NOD1), one of the members of the pattern recognition receptors (PRRs) family of innate immunity, has been related to numerous pathologies, such as cancer, diabetes, or cardiovascular diseases." (PMID 34066406, 2021).